EGFR (epidermal growth factor receptor)
Diseases named in the same sentence as EGFR in open-access papers (continued):
Sharing a sentence is not in itself a finding about the gene and the disease.
breast carcinoma (continued). "SorLA silencing inhibits 3D spheroid growth induced by heregulin-enriched stroma, and sensitizes metastatic breast cancer cells to the HER2/EGFR dual tyrosine kinase inhibitor neratinib in an in vivo xenograft model of brain tumors." (PMID 33420373, 2021). "Human epidermal growth factor receptor (EGFR) 2 (HER2) is overexpressed/amplified in about 25% of all breast cancers, and EGFR is overexpressed in up to 76% and amplified in up to 24% of triple-negative breast cancers (TNBC)." (PMID 34203351, 2021). "Epidermal growth factor receptor (EGFR) serves as a co-target for dual/pan-EGFR-inhibitors in breast cancer." (PMID 33356806, 2021). "Aggressive breast cancers overexpress Epidermal Growth Factor Receptor (EGFR) family members where ~ 25% of breast cancer patients overexpress human epidermal growth factor receptor 2 (HER2) and ~ 15% overexpress the EGFR1 isoform." (PMID 34074257, 2021). "We further demonstrated that the SHP-1–induced suppression of EGFR inactivated the Ras/Erk/GSK3β pathway, thus enhancing understanding of the molecular mechanism of breast cancer progression, given that this pathway is known to be dysregulated in many cancers." (PMID 34591414, 2021). "By in silico screening, a series of C7-hydroxyproton substituted chrysin derivatives exhibited EGFR inhibiting possessions against breast cancer." (PMID 33858433, 2021). "Poziotinib was terminated in 3 clinical studies for NSCLC (patients having EGFR or HER2 exon 20 insertion mutation), breast cancer (In HER2+ breast cancer patients, poziotinib in combination with T-DM1) and adenocarcinoma of lung stage IIIB and IV." (PMID 34885957, 2021). "The pro-metastatic effect of EGFR is further supported by studies reporting a correlation of EGFR and metastasis in human breast cancer probes." (PMID 33670586, 2021). "Here we employ deep learning to classify breast cancer cell types based on the trajectories of epidermal growth factor receptor (EGFR)." (PMID 34390568, 2021). "In recent studies, EGFR has been shown to be a promising oncological target for the treatment of TNBC because it is frequently observed in TNBC compared to other breast cancer subtypes." (PMID 34681198, 2021). "Our results indicate that CSMD1 cross-talks with the EGFR endosomal trafficking cascade in a way that renders highly invasive breast cancer cells sensitive to chemotherapy." (PMID 34404439, 2021). "In breast cancer treatment, Navitoclax has been proven to enhance the effectiveness of epidermal growth factor receptor (EGFR)-targeted antibody-drug conjugates for TNBC treatment in animal experiments." (PMID 33816265, 2021). "In another study, exosomes were used to deliver let-7a miRNA targeting EGFR-overexpressing breast cancer cells in mice." (PMID 34489693, 2021). "Recently, EA has been reported to have synergistic antitumor effects in breast cancer when combined with irreversible EGFR TKIs." (PMID 34122668, 2021). "Overall, the “reciprocal priming” between FGFR and EGFR is a novel mechanism to coordinate the trafficking and the signalling outputs of these two RTKs in breast cancer cells." (PMID 34086370, 2021). "The overexpression of EGFR, another upregulated hub gene, leads to poor prognosis in breast cancer patients." (PMID 34754042, 2021). "Breast cancer usually presents the following proteins: estrogen receptor (ER), progesterone receptor (PR), epidermal growth factor receptor (EGFR), and human epidermal growth factor receptor 2 (HER2)." (PMID 34135981, 2021). "The development of resistance was analyzed following long-term exposure of BT474 and SKBR3 breast cancer cells to EGFR-targeting small molecules (gefitinib, erlotinib) and of SW48 colon cancer cells to an anti-EGFR monoclonal antibody cetuximab." (PMID 33445730, 2021). "Numerous studies showed that the PI3K/AKT/mTOR signaling pathway activates upstream receptors (EGFR and PDGF) and is mutated in a variety of cancers, including breast cancer, gastric cancer, and NSCLC." (PMID 34580719, 2021).
breast carcinoma (continued). "EVs-miR-182-5p promotes tumorigenesis and metastasis of breast cancer cells by regulating the CMTM7/EGFR/AKT signaling axis." (PMID 34294040, 2021). "al engineered exosomes to express the peptide GE11 to efficiently deliver miRNA to epidermal growth factor receptor (EGFR)-expressing breast cancer cells." (PMID 33750417, 2021). "The use of specific anti-tumor antibodies has transformed the solid cancer therapeutics landscape with the relative successes of therapies such as anti-HER2 in breast cancer, and anti-EGFR in HNSCC and colorectal cancer." (PMID 33520112, 2021). "In their study, they further modified this nanovesicle with an epidermal growth factor receptor (EGFR) antibody through bispecific antibodies to target breast cancer." (PMID 34202452, 2021). "ErbB receptor tyrosine kinases epidermal growth factor receptor (EGFR) and ErbB2 (neu, HER2) are often overexpressed, amplified, or mutated in many forms of cancer, including breast cancer, making them important therapeutic targets." (PMID 34944912, 2021). "Another study investigated the effects of both the SPIONs coupled with anti-EGFR (Epidermal Growth Factor Receptor) antibody and aptamer in targeting breast cancer cells." (PMID 34663344, 2021). "The HS-nanoparticles targeted the breast cancer cells via HB-EGF/EGFR-mediated interactions in both the 2D-monolayer and in the 3D-complex coculture tumor model." (PMID 34163672, 2021). "The expression level of SQSTM1 positively correlates with the expression level of EGFR in breast cancer." (PMID 34830108, 2021). "Lastly, HOIPIN-8 suppresses breast cancer cell proliferation and clonogenicity by blocking EGFR-mediated NF-κB activation." (PMID 34769306, 2021). "Then we identified EGFR as a specific and direct target of SHP-1, thus improving understanding of the mechanisms underlying breast cancer progression." (PMID 34591414, 2021). "EGFR is found to be expressed aberrantly in many solid tumors like lung, colorectal cancers, head and neck squamous cancers, and breast cancers, where around 25–30% cases are attributed to EGFR overexpression." (PMID 33530291, 2021). "Exosomes are reprogrammed to express CD3-specific antibodies for T cells and EGFR antibodies for EGFR-expressing breast cancer cells." (PMID 34616851, 2021). "EGFR TKIs have been reported to activate autophagy as a cytoprotective response in various cancer cell lines, including breast cancer, lung cancer, squamous cell carcinoma, and transitional cell carcinoma." (PMID 34207383, 2021). "Our data suggest that primaquine can be used in breast cancer treatment as it targets the nuclear translocation of EGFR." (PMID 34884765, 2021). "The MDA-MB-468 (MDA468) cell line was identified as having the highest EGFR mRNA expression compared with other breast cancer cell lines." (PMID 34504181, 2021). "The co-existence of high levels of HER3 and EGFR is correlated with worse breast cancer-specific and distant metastasis-free survival for patients with TNBC." (PMID 34203351, 2021). "We also examined the relationship between TINCR and EGFR protein expression in 120 breast-cancer samples from HMUCC, and the results showed that the EGFR level was higher in TINCR high-expression tissues than in TINCR low-expression tissues." (PMID 33446634, 2021). "Specifically, we designed and constructed a bi-functional aptamer linking EGFR and C3b/iC3b, and used it in a cell-based assay to cause lysis of MDA-MB-231 and BT-20 breast cancer cells, with either human or mouse serum as the source of complement factors." (PMID 35052426, 2021). "The combination of Tamoxifen and growth factor receptor kinase inhibitor (RKI) is also one of the main therapeutic approaches for Tamoxifen‐resistant breast cancer with overexpression of EGFR or HER‐2." (PMID 34651424, 2021). "In our previous studies with breast cancer cells (except for the EGFR-high triple-negative breast cancer cells), fascin inhibitors did not inhibit the growth of these tumor cells." (PMID 34070777, 2021).
breast carcinoma (continued). "Our present data showed that the expression of SHP-1 was significantly positively correlated with ER and PR expression levels and negatively associated with EGFR expression levels, thereby suggesting that SHP-1 plays an important role in breast cancer." (PMID 34591414, 2021). "EGFR/HER2 overexpression in breast cancer increases breast cancer malignancy by upregulated cancer cell survival, invasion and metastasis, maintenance of stem cell-like tumor cells, and resistance to targeted therapies." (PMID 34074257, 2021). "Currently, the targeted therapeutic drugs that block the EGFR signaling pathway in breast cancer research are mainly anti-EGFR monoclonal antibodies (cetuximab)." (PMID 34198652, 2021). "Apart from these, the growth factor of the epidermis and its receptors (EGFR) in breast cancer are continuously often overexpressed." (PMID 34221232, 2021). "For example, a research team engineered human embryonic kidney (HEK) cells to produce exosomes able to target breast cancer cells overexpressing epidermal growth factor receptor (EGFR)." (PMID 34568341, 2021). "EPA/DHA is reported to decrease the levels of VEGF and phosphorylated EGFR in MDA-MB-231 breast cancer cells and inhibit microvascular formation in tumor-bearing mice." (PMID 33805447, 2021). "Basal-like breast cancers frequently demonstrate evidence of epithelial-mesenchymal transition and have a high frequency of EGFR amplification." (PMID 34831127, 2021). "In vitro investigations revealed cetuximab-conjugated TPGS micelles exhibited remarkably higher cellular uptake as compared to unconjugated NPs on MDA-MB-468 and MDA-MB-231 breast cancer cells which overexpressed EGFR on the cell surface." (PMID 34959321, 2021). "In our previous work, we showed that RANK-c interacts with EGFR receptor in breast cancer cells affecting EGFR phosphorylation status and downstream signaling." (PMID 34828291, 2021). "A protein commonly expressed on tumor cells is EGFR and is a common target in other cancers such as colorectal and breast cancer." (PMID 34203051, 2021). "Accumulation in liver has also been reported in studies on the administration of EGFR-bearing exosomes with high affinity for hepatic tissues, and in tumor tissues in a xenograft model of breast cancer." (PMID 33800282, 2021). "EGFR frequent overexpression and/or hyperactivation in breast carcinomas play an active role in facilitating brain-specific metastatic spread." (PMID 33672529, 2021). "Excessive clusters of EGFR (100 times more than normal cells) in the extracellular domain of breast cancer cells and a higher binding affinity towards EGF make it a rational target for its ligand." (PMID 33530291, 2021). "We observed that the mutations/deletion of NEDD4L was mutually exclusive with the activation of AKT signaling pathway (PTEN deletion/mutations, epidermal growth factor receptor (EGFR), PI3KC, or AKT1 mutations/amplification) in breast cancers." (PMID 34278744, 2021). "Neratinib (Nerlynx®) is an irreversible HER2 and EGFR TKI approved for the treatment of HER2-positive breast cancer." (PMID 34207383, 2021). "In order to define a proper in vitro system for subsequent studies, we analyzed different breast cancer cell lines for expression of the HER family receptors (EGFR, HER2, HER3 and HER4)." (PMID 33692466, 2021). "Conversely, treatment of breast cancer cell lines with SP resulted in overexpression of Her2/neu and EGFR and affected the response to anti-EGFR and anti-Her2 agents." (PMID 34086748, 2021). "Using MDA-MB-231 breast cancer cells as a model, the capture probe based on quantum dots was used to recognize the surface biomarkers EGFR and ICAM-1, which induced a chain-like chain replacement reaction." (PMID 34360949, 2021). "In turn, M2-like TAMs activate breast cancer cells through EGFR/PI3K/Akt signaling, providing feedback to upregulate SGLT1 and promote tamoxifen resistance and accelerate tumor growth in vitro and in vivo." (PMID 34006822, 2021).
breast carcinoma (continued). "In previous studies, YB-1 is coordinately expressed with EGFR in primary human breast cancer and cervical cancer specimens, and the expression of EGFR is dependent on functional YB-1." (PMID 34696665, 2021). "Accordingly, breast cancer cells expressing EGFR secrete CSF-1 and attract macrophages, which secrete EGF in the vicinity of cancer cells, thus permitting cancer cell migration." (PMID 34206026, 2021). "The expression of VEGF-B (log FC = 1.5, p = 0.014) and EGFR (log FC = 1.6, p = 0.017) genes was found to be upregulated in mammary carcinoma tissue (n = 48), compared to paired adjacent normal tissue." (PMID 34679042, 2021). "First, we assessed the gene expression of EGFR in a series of breast cancer cell lines using a publicly available microarray dataset (GSE41313)." (PMID 34879870, 2021). "The capability of an analog of chrysin to inhibit EGFR was reported in a breast cancer stem cell model." (PMID 33858433, 2021). "EGFR inhibition through TKIs in breast cancer has been tested in triple-negative disease settings with limited clinical benefit for patients." (PMID 34828291, 2021). "Nuclear EGFR (nEGFR) drives resistance to anti-EGFR therapy and is correlated with poor survival in breast cancer." (PMID 34884765, 2021). "The stimulation of GPER1 activates Ca2+ release, ERK1/2, PI3K action and stimulation of epidermal growth factor receptor (EGFR) transcription in breast cancer cell lines." (PMID 34089761, 2021). "Nucleic acid aptamers that can recognize specific target molecules are used to increase the specificity of targeting the PSMA aptamer in prostate cancer xenografts, EGFR aptamer in breast cancer xenografts, and survivin in colorectal cancer xenografts." (PMID 34830787, 2021). "We used breast cancer cell lines to analyze the effects of CDK8/19 inhibitor senexin B on the development of resistance to small-molecule EGFR inhibitors gefitinib and erlotinib." (PMID 33445730, 2021). "Next, the dual inhibition of FAK and epidermal growth factor receptor (EGFR) cooperatively led to apoptosis of breast cancer cells via caspase-3 and caspase-8 activation, cleavage of PARP and caspase-3-mediated AKT degradation." (PMID 33562737, 2021). "Higher frequencies of mutations in neurofibromatosis (NF1), ataxia telangiectasia and Rad3 related (ATR), and breast cancer (BRCA1) genes have been reported in EGFR-mutant SCCs compared to EGFR-mutant adenocarcinomas." (PMID 34572868, 2021). "As primaquine impairs the endocytosis-mediated degradation of EGFR, we assessed nEGFR expression in breast cancer." (PMID 34884765, 2021). "In order to confirm the binding of 6-gingerol to EGF receptor, we treated the breast cancer cells with recombinant human EGF (25 ng/mL) which showed an increase in the expression of phosphorylated EGFR which significantly downregulated by 6-gingerol." (PMID 33925065, 2021). "Whole genome sequencing of tumors derived from a mouse model of breast cancer, MMTV-PyMT, identified a highly conserved mutation in PTPRH, which increases the phosphorylation of EGFR." (PMID 34187934, 2021). "Phosphoproteomics reveal that FGFR recycling ligands induce specific EGFR phosphorylation that in turn alters FGFR2b trafficking and signaling in breast cancer cells." (PMID 34086370, 2021). "The effect of SP on cellular proliferation was previously observed in breast cancer cell lines where the use of anti-SP antibodies resulted in the downregulation of EGFR and Her2/neu." (PMID 34086748, 2021). "EGFR is more predominant in TNBCs than other breast cancers, and usually correlates with tumor invasion and poor prognosis." (PMID 34359650, 2021). "Specifically, FGFR recycling ligands induce phosphorylation on EGFR at the non‐catalytic threonine T693 (T669 in the UniProt sequence P00533) that reciprocally affects both FGFR and EGFR signalling outputs in breast cancer cells." (PMID 34086370, 2021).
breast carcinoma (continued). "For instance, the inhibition of both FAK and EGFR signaling pathways was demonstrated to induce apoptosis in breast cancer cells." (PMID 33562737, 2021). "The modified Salmonella, was used against mouse models of EGFR-positive colon and breast cancer to effectively target the tumour microenvironment and selectively kill the EGFR-expressing tumour cells, inhibiting further tumour growth." (PMID 34236075, 2021). "HER2- and EGFR-positive breast cancer cells resistant to lapatinib, a tyrosine kinase inhibitor that blocks the activation of the EGFR and HER2 pathways, revealed increased activity of HPSE." (PMID 33494442, 2021). "Our study of primaquine and chloroquine provides a rationale for targeting EGFR signaling components in the treatment of breast cancer." (PMID 34884765, 2021). "For example, TGFA can regulate the transformation of mammary epithelial cells, and TGF-α and epidermal growth factor receptor (EGFR) are overexpressed in human breast cancer tissues and various breast cancer cell lines." (PMID 32020849, 2021). "Breast cancer is commonly separated into Luminal A (LumA), Luminal B (LumB), epidermal growth factor receptor ERBB2/HER2-overexpressing (HER2+), and basal epithelial-like (BL) based on gene expression profiles." (PMID 33574966, 2021). "For HER2/EGFR double-positive breast cancer cells, our present study suggests that RhoB functions as a tumor suppressor because its constitutive degradation by the CUL3/KCTD10 E3 complex is essential for cell proliferation of SKBR-3 cells." (PMID 34187934, 2021). "Metastatic cascade is regulated by epidermal growth factor receptor (EGFR)/ErbB1 and ErbB2/Her 2 receptors whose overexpression form the most aggressive kind of breast cancer." (PMID 35431911, 2021). "Based on the results of western blotting, it was confirmed that they have inhibitory activity for the generation of phosphorylated Akt in the EGFR-overexpressed breast cancer cell line MDA-MB-468." (PMID 34681198, 2021). "A positive correlation was found among PET-CT SUVmax, EGFR, glycolytic activity, and PI3KCA mutation status in NSCLCs and breast carcinomas." (PMID 35029792, 2021). "MAP2K1 expression was strongly correlated with expressions of EGFR (r= 0.252–0.62) in liver, lung, kidney, colon, head and neck, and breast cancers but negatively correlated in glioblastoma (r = −0.062)." (PMID 33842373, 2021). "Lapatinib (Tykerb®, GlaxoSmithKline, London-Brentford, UK) is such an inhibitor targeting the receptor tyrosine kinase and EGFR-member ErbB2 to treat breast cancer (BC)." (PMID 33917267, 2021). "In mammary tumors, for example, TAMs secrete epidermal growth factor receptor (EGFR) family ligands, including heparin-binding EGF-like growth factor (HB-EGF), and activate STAT3-related signaling pathways to fuel tumor cell proliferation." (PMID 34178692, 2021). "We therefore sought to determine the clinical prognostic significance of our observed highly significant correlation between resistin and EGFR expression in breast cancer tissue." (PMID 33313320, 2020). "The current study aims to investigate if abnormal pre-treatment serum levels of EGFR and EGFR ligands are present in women with early-stage breast cancer and if up- or downregulation of EGFR and EGFR ligands occur in defined patient subgroups." (PMID 32317675, 2020). "The findings of the present study is a stepping stone for further investigations of the clinical potential of using blood levels of EGFR and EGFR ligands in tailored treatment of breast cancer in order to improve outcome for the patients." (PMID 32317675, 2020). "Alterations to the EGFR copy number are often observed in head and neck squamous cell, colorectal, squamous non-small-cell lung, and breast cancer." (PMID 33333826, 2020).